MIR3118-4 (microRNA 3118-4)
Synonyms: hsa-mir-3118-4
Gene: MicroRNA gene on chromosome 15 (21,843,750 to 21,843,824, forward strand). Ensembl gene ENSG00000265793.
Homologues: Paralogues in human: MIR3118-2 (100% identical), MIR3118-3 (100% identical).